RNU7-119P (RNA, U7 small nuclear 119 pseudogene)
Gene: Small nuclear RNA gene on chromosome 3 (73,593,940 to 73,594,002, reverse strand). Ensembl gene ENSG00000239119.
Homologues: Orthologues: chimpanzee U7 (100% identical). Paralogues in human: RNU7-160P (75% identical), RNU7-171P (75% identical), RNU7-35P (75% identical), RNU7-85P (75% identical), RNU7-12P (73% identical), RNU7-13P (73% identical), RNU7-154P (73% identical), RNU7-181P (73% identical), RNU7-29P (73% identical), RNU7-52P (73% identical), RNU7-57P (73% identical), RNU7-60P (73% identical), and 142 more.